CD4 (CD4 molecule)
Diseases named in the same sentence as CD4 in open-access papers (continued):
Sharing a sentence is not in itself a finding about the gene and the disease.
Immunodeficiency (continued). "The reason may be that the benefit gained from disease control is partially offset by increased mortality from infectious complications, especially in patients whose CD4+ cell count below 50/μL, with severe immunodeficiency and those receiving rituximab maintenance therapy." (PMID 36056692, 2022). "Similarly, the pyroptosis of CD4+ T cells led to immunodeficiency in HIV." (PMID 35432318, 2022). "Immunodeficiency-associated Burkitt’s Lymphoma is predominant in HIV patients with CD4 counts usually above 200 cells/μL and may be present in other forms of immunodeficiencies such as patients who have undergone immunosuppressive therapy due to the fact of organ transplant." (PMID 35053275, 2022). "In addition, evidence from previous studies indicates that CD4 + T cells are exhausted and may be critical in collective immune dysfunction." (PMID 36230507, 2022). "Findings revealed that CD4+ Tconv was significantly enriched in carbohydrate metabolism, signal transduction, translation, signaling molecules and interaction, endocrine and metabolic disease, immune disease, cardiovascular disease, immune system, and cell motility-related pathways." (PMID 35603183, 2022). "Furthermore, elucidating how lncRNAs modulate CD4+ T-cell differentiation in disparate immune diseases may provide a basis for the pathological mechanism of immune-mediated diseases." (PMID 35794862, 2022). "The inclusion of patients with CD4 > 350 cell/mm impairs us to extrapolate results to immunological non-responders, which may be the population that hypothetically benefits most from an intervention addressing immune dysfunction." (PMID 35928688, 2022). "Finally, for CNSs to provide novel targets and strategies, it is necessary to explore the mechanisms whereby CNSs could be manipulated to produce sufficient and stable effector CD4+ T cells relevant to the treatment of immune diseases and cancer." (PMID 35812386, 2022). "After early and regular cART treatment, there were no significant changes in CD4 T cell counts or DTI metrics, suggesting that absolute CD4 T cell counts may not accurately reflect the risks to HIV-infected individuals because immune dysfunction persists even when CD4 counts are back to normal." (PMID 36713432, 2022). "Significant decrease in the CD4/CD8 ratio may indicate an immune disorder in PD." (PMID 34282123, 2021). "Besides, all patients, except three, had CD4 + T-cells > 350/mm3, indicating no severe immune deficiency." (PMID 33012282, 2020). "Inability to mount a CRP response could be explained by low CD4 count of 127 ± 99 μl/ml in their study as compared to 520 ± 236 μl/ml in the current study, as severe immunodeficiency (< 50 μl/ml) is reported to significantly limit inflammatory response, in addition to an increased risk of death." (PMID 31331321, 2019). "Finally, we assessed whether lower airway bacterial community states were related to systemic immune dysfunction as indicated by CD4 status." (PMID 30857553, 2019). "Furthermore, different CD4+ and CD8+ T cell subsets are associated with specific outcomes in both infectious diseases and immune disorders, which implies that the T cell phenotype, in addition to the number of circulating CD4+ T cells, is crucial in determining the outcome of CM." (PMID 31319498, 2019). "However, subsequent measurements of peripheral blood T cell subsets, including a recent peripheral lymphocyte phenotyping revealed a gradual reduction in both CD4+ T cell and CD45RA+ naïve CD4+ T cell counts, which is consistent with a transition to a combined immunodeficiency disorder." (PMID 30987377, 2019). "However, these viral properties did not cause accelerated CD4+ T cell depletion and immunodeficiency in AGMs, indicating that these intrinsic viral properties are not sufficient to counteract effective host protective mechanisms." (PMID 29636452, 2018).
Immunodeficiency (continued). "For example if children with poorer health were less likely to have CD4 measurements performed, this would violate the assumption of values “missing at random” 30 and lead to an underestimation of the proportion of children starting cART with severe immunodeficiency." (PMID 30614622, 2018). "However, the lutein level was lower in the cART group presenting low CD4+ T cell counts, suggesting that both the use of cART and immunodeficiency could influence lutein levels." (PMID 29992171, 2018). "A lower nadir CD4+ T cell count has also been shown to have an inverse relationship with the development of NADC, again suggesting that residual immune dysfunction despite restoration of peripheral CD4+ T cell counts may be important in the pathogenesis of NADC." (PMID 29443936, 2018). "Additionally, increased relative abundance of Fusobacterium was also significantly correlated with reduced naïve CD4 T-cells, increased CD4 T-cell activation and increased regulatory T-cells measured in peripheral blood, all markers of persistent immune dysfunction in HIV infection." (PMID 30250162, 2018). "The CD4 cells were indeed very low (median; clinical model: 58 cells/μl; clonal model: 91 cells/μl) for X4-tropic patients, but also the R5-tropic patients had an advanced immunodeficiency (clinical model: 132 cells/μl; clonal model: 125/μl) when fpr10% was used." (PMID 28061826, 2017). "Importantly, these observations point to immune dysfunction in young HIV that may be overlooked based on normalization of CD4 counts and suppression of plasma virus load with ART." (PMID 28448963, 2017). "This could be the result of advanced immunodeficiency represented by patient's low CD4 cell count." (PMID 27239353, 2016). "In addition, activated macrophages could favor the depletion of both uninfected CD4+ T cells and CD8+ T cells leading to immune deficiency." (PMID 25835530, 2015). "If the risk of anal cancer could be largely attributable to HIV-related immunodeficiency as assessed by decreased CD4+T cell counts, early diagnosis of HIV infection and early starting ART might be key point to prevent anal cancer development among HIV infections." (PMID 25923768, 2015). "In our study patients had no severe immune deficiency with a median CD4 cell counts above 500 cells/mm3, however their median CD4 cell count nadir was low, and a low nadir CD4 cell count has been associated with an increased risk of non-AIDS related cancers such as HPV-related anal cancers." (PMID 26642314, 2015). "Some studies reported immunodeficiency mice which lack T-cells were resistant to MPTP, and also found in MPTP-treated T cell receptor beta (TCR β−), CD4− and CD8−-deficient mice, transferred CD4+ T cells accelerated nigral degeneration, whereas CD8+ T cells did not." (PMID 24933638, 2014). "However, since patients with IRIS usually have low CD4 T cell counts, aggravation of immunodeficiency may have fatal consequences in this particular group." (PMID 25587282, 2014). "A CD4 count decrease was associated with CIN of grade 3 in a subset of 241 women infected with non-HPV16 carcinogenic HPV suggesting that even among women already harbouring carcinogenic HPVs, immunodeficiency was associated with the presence of high grade CIN." (PMID 24595037, 2014). "Collectively, these results suggest that a persistently low CD4/CD8 ratio during ART may be a marker of persistent immune dysfunction and inflammation, and that monitoring of this ratio—which can be readily done in most clinics with current assays—may be clinically useful." (PMID 24831517, 2014). "This could be assumed that cell mediated immune deficiency in these patients was not from CD4 lymphocytopenia like in HIV infected patients." (PMID 24094273, 2013).
Immunodeficiency (continued). "In order to confirm that the phenotype observed in CCR6KO and CXCR3KO mice was specifically due to ablation of CCR6 and CXCR3 in T cells (not a general immune deficiency), CD4+ T cells from CCR6KO or CXCR3KO mice after DS were adoptively transferred to T cell-deficient RAG1KO mice." (PMID 24223818, 2013). "The finding that HIV patients who started antituberculous therapy with unknown CD4 cell count had higher mortality has been described elsewhere and it suggests that patients who lacked a baseline CD4 cell count, actually, presented advanced immunodeficiency." (PMID 23049842, 2012). "The immunodeficiency and natural infectious history of alkylator-resistant, corticosteroid-treated patients appears to have changed with the administration of purine analogs, which has been complicated by severe and unusual infections due to sustained reduction of CD4-positive T lymphocytes." (PMID 23205258, 2012). "In this study, CD4+CD25+ Treg cell depleted mice were shown to be susceptible to the CIS-induced development of depression-like behaviors, indicating that stress induced depression may be considered a pathogenic immune disorder." (PMID 22860054, 2012). "Thus, facets of immune function other than CMI (as assessed by DTH) may also be associated with worse HIV clinical outcomes, and such aspects of immune dysfunction appear to be evident in those with relatively high CD4 cell counts." (PMID 22457767, 2012). "The concept of "immunological surveillance" could be an explanation: the decrease of CD4+ T cells and other immune dysfunctions induced by HIV infection lead to a decrease of both the control of oncogenic viruses like EBV and the destruction of malignant precursors." (PMID 21443771, 2011). "Thus, the CD4+CD25+CCR4+ leukemia T cells with increased Treg function may also contribute to the clinically observed cellular immunodeficiency in ATL patients." (PMID 19654865, 2009). "However, more information on the progression to immunodeficiency may be found in the detailed subset composition of CD4+ and CD8+ T cells, but this is currently restricted to research studies." (PMID 18036256, 2007). "Treatment with rituximab was scheduled but repeat viral screening revealed newly diagnosed HIV infection with advanced immunodeficiency (HIV-RNA 1500000 copies/mL, CD4 + lymphocyte count 135/uL (12%) and CD4/CD8 ratio 0.19 at baseline)." (PMID 41555103, 2026). "Lower baseline CD4 count and older age were the strongest predictors of incomplete immune reconstitution, with individuals initiating ART at advanced stages of immunodeficiency showing markedly reduced probability and slower tempo of immune normalization." (PMID 41909684, 2026). "Immunodeficiency in AT is characterized by a decrease in the numbers of CD3 + CD4 + T, CD20 + B, and CD4 + CD45RA + naïve T cells." (PMID 40457861, 2025). "Another important mechanism was the immunodeficiency induced by HIV, characterized by depletion of CD4+ T-cells and compromised immune function, impairing the host’s capacity to mount an effective immune response against new HPV infections." (PMID 41295517, 2025). "The PCNSL develops in patients with more severe immunodeficiency, usually at a median CD4 of 10 cells/μL, compared with patients with systemic NHL, in which disease develops at a median CD4 count of 189 cells/μL." (PMID 40951615, 2025). "Downregulated genes in CD69+ CD4+ T cells were involved in cell adhesion (PTPRC; -0.38log2FC), differentiation (CD44; -0.38log2FC), and immunodeficiency (IL7R; -0.42log2FC) pathways." (PMID 41208955, 2025). "The increased PD-1 and PD-L1 expression on CD4+ and CD8+ T cells suggests that T-cell exhaustion is a major contributor to immune dysfunction in periimplantitis." (PMID 40217900, 2025). "Another study demonstrated a reduction in activation of CD4 cells, proinflammatory cytokine production IL-2, prevention of CD4/CD8 derangement and lymphocyte directed immune dysfunction." (PMID 40336073, 2025).
Immunodeficiency (continued). "Their decline, along with a reduced CD4/CD8 ratio, reflects immune dysfunction and has been widely used to assess immune status and lymphoma risk in PLWH." (PMID 40723865, 2025). "Resting memory CD4+ T cells (r = -0.192, P < 0.05) and activated memory CD4+ T cells (r = -0.215, P < 0.05) exhibited strong negative correlations, suggesting that a reduced population of memory T cells may contribute to immune dysfunction in high-risk patients." (PMID 41293172, 2025). "To better understand the impact of immune dysfunction on survival outcomes of HL and HIV-HL patients, we investigated the prognostic value of CD4+ T-cell counts, CD8+ T-cell counts, and the CD4/CD8 ratio." (PMID 40969752, 2025). "In conclusion, our study demonstrates that downregulation of the TCR/CD3 complex in HTLV-1-infected CD4+ T cells significantly impairs TCR signaling, contributing to immune dysfunction in HAM patients." (PMID 40004169, 2025). "Specific depletion of PD-1+ CD4+ and CD8+ T cells appears to have induced a form of CAR-mediated immunodeficiency with an attenuation of cellular and humoral responses, which likely exacerbated SIV infection." (PMID 38557496, 2024). "A range of CD4/CD8 ratios are represented; however, small patient populations are being represented for some of the less common immunodeficiencies." (PMID 39728019, 2024). "Therefore, from an immunologic standpoint, HIV‐l immunodeficiency is seen as a graded severity of CD4 T cell depletion that is distributed over time, influenced by unknown cofactors, and linked to a spectrum of increasing clinical severity that corresponds to the degree of CD4 T cell depletion." (PMID 39319247, 2024). "According to the Centers for Disease Control and Prevention, CD4+ T-cell counts of less than 200 cells/mm3 are categorized as stage 3 HIV infection, enhancing the immunodeficiency condition." (PMID 39066175, 2024). "We have shown the potential benefits of selenium supplementation on body composition, replenishment of CD4+ T cells and potentially beneficial transcriptional changes in CD8+ T cells that could improve negative effects associated with inflammation, metabolic and immune dysfunctions." (PMID 39351495, 2024). "Our study revealed a significant reduction in CD4+ T cells in TB-COPD patients, accompanied by a decrease in the CD4+/CD8+ ratio, indicating severe cellular immune dysfunction in these patients." (PMID 39432654, 2024). "Between 2011 and 2020, the absolute numbers of children starting treatment decreased in the cohort, with improvements in the median CD4 counts at ART start and decline in the overall proportions with severe immunodeficiency." (PMID 37708128, 2023). "At the time of first TB episode, our study patients were with marked immunodeficiency and high HIV-RNA viral load: CD4 count <350 cells/mm3 was in 42.9% and <50 cells/mm3 –in 23.5% of patients and only 15.3% had viral load < 200 copies/mL." (PMID 36952578, 2023). "Additionally, the incidence of subsequent recurrent pneumonia was higher in the PB group than in the non-PB group, suggesting more local mucosal injury and immune dysfunction in the bronchi of the PB group, which is also associated with the imbalanced CD4+/CD8+ ratio described earlier." (PMID 36633659, 2023). "The abnormal ratio of CD4+/CD8+ T cells, as an indicator of immune regulation, suggests immune dysfunction." (PMID 37318361, 2023). "Again, a persistently elevated CD8+ T cell count, which leads to partial restoration of the CD4/CD8 ratio, has an important prognostic significance on clinical outcomes, immune dysfunction, and HIV-1 reservoir size in long-term treated patients." (PMID 36672667, 2023). "A T cell subpopulation analysis was performed in 21 patients with pulmonary infection, and 13 (61.9%) had a ratio of CD4+ to CD8+ T lymphocytes below two, which revealed immune dysfunction in these patients." (PMID 38098502, 2023).
Immunodeficiency (continued). "Around these age inflection points, the proportion of immune cells, including that of CD4+ T cells, CD8+ T cells, and γδ T cells, changed considerably and was generally considered to be related to the occurrence of cancers and some immunodeficiency diseases." (PMID 37589027, 2023). "Early diagnosis and timely initiation of treatment in early childhood to prevent growth retardation and immunodeficiency are critical to improving APH growth and CD4 outcomes by the time they reach adulthood." (PMID 35255197, 2022). "Infection leads to a progressive decline in CD4+ lymphocytes, inversion of the CD4:CD8 ratio, and in some cases progression to severe immunodeficiency like that seen in humans infected with HIV." (PMID 36298731, 2022). "The CD4+ T and CD4/CD8 ratio in cells is significantly decreased in PD patients compared with healthy controls, indicating an immune disorder in PD." (PMID 36567855, 2022). "ART efficiently suppresses viral replication, which indirectly increases CD4+ T cell count, improves the CD4/CD8 ratio and repairs immune disorders." (PMID 35351857, 2022). "The crucial role of CD4+ and CD8+ T cells in shaping and controlling immune responses during immune disease and cancer development has been well established and used to achieve marked clinical benefits." (PMID 35222392, 2022). "Given a relatively low predictive value of serologic tests in patients with immune disorders, including HIV-infection with CD4+ count <100 cells/mm3 and molecular testing characterized by higher sensitivity and specificity, is proposed." (PMID 35160090, 2022). "Increasing evidence has indicated that changes in CD4+CD25+ Tregs numbers and function lead to immune disorders." (PMID 34758202, 2022). "On the other hand, it can interfere with the immune disorder of asthma and control the inflammatory reaction by decreasing CD8 +T and increasing the level of CD4 +T cells." (PMID 35101086, 2022). "TIPE2 improves the PHSML-mediated CD4+T cells dysfunction by regulating TLR2/TLR4 pathway, providing a new intervention target following hemorrhagic shock-induced immune dysfunction." (PMID 35572554, 2022). "The fact that, for safety reasons, a basal CD4 T cell count above 350 cell/mm was required for inclusion, excluded immunological non-responders from participation, which may be the population that hypothetically benefits most from an intervention addressing immune dysfunction." (PMID 35267967, 2022). "In the immune infiltration analysis of this study, resting CD4+ memory T cells and NK cells were significantly reduced among the 22 subtypes of immune cells in the case groups compared to the control group, which may be the main reason for immune dysfunction in KD." (PMID 35924269, 2022). "For example, CD4 count is a good indicator of immune status, and is routinely used for the management of patients with HIV infection and other immunodeficiency disorders." (PMID 35546670, 2022). "HIV-1 weakens the patients' defense system via targeting and destroying immune cells that express CD4 receptor and either the CCR5 or the CXCR4 co-receptors, especially CD4+ T cells, leading to immunodeficiency in the last stage of disease." (PMID 33451365, 2021). "The results of this study show that the absolute values of CD3+, CD4+, CD8+, CD3-CD19+, and NK cell counts were significantly lower in the EBV-HLH group than in the EBV-IM group, indicating a serious immunodeficiency in the EBV-HLH cases." (PMID 33413556, 2021). "Functioning as an immunosuppressive group, CD4+ CD25+ Tregs maintain immunologic self-tolerance and negatively modulate the occurrence and development of immune disorders." (PMID 33575330, 2021). "By progressively destroying HIV-infected CD4+ T-cells, HIV infection induces profound cellular immunodeficiency and, hence, an inability of the immune system to function in a competent manner." (PMID 35069530, 2021).